NEK6 (NIMA related kinase 6)
Diseases named in the same sentence as NEK6 in open-access papers (continued):
Sharing a sentence is not in itself a finding about the gene and the disease.
cancer (30 papers, 2007 to 2025). A tumor composed of atypical neoplastic, often pleomorphic cells that invade other tissues. "It is worth noting that NEK6 overexpression is associated with tumorigenesis and cancer progression in several solid tumors." (PMID 35096064, 2022). "In recent years, altered expression and activity of NEK6 were associated with several types of cancer, such as liver, prostate, gastric, colorectal, breast, serous epithelial ovarian, thyroid, and retinoblastoma cancers." (PMID 32294979, 2020). "Similar to Nek2, Nek6 is overexpressed in tumors from a variety of tissues including breast, uterus, colon, ovary, thyroid, and cervix, as well as a number of associated carcinoma cell lines." (PMID 22040655, 2011). "Like Nek6, Nek7 has been linked to several cancers due to its high levels of expression in them." (PMID 35409400, 2022). "The expression profiles of NEK6 across cancers and OC were explored using bioinformatics analysis, and its expression in OC patients was detected by immunohistochemical (IHC) staining." (PMID 39895790, 2025). "There is evidence that NEK6 is increased in several malignant human cancer cells including breast, colon, lung, kidney, rectum, thyroid, ovarian, prostate, pancreas and small intestine cancers, and correlates with patient clinical prognosis." (PMID 41560755, 2025). "Cox regression analysis revealed that NEK6 expression is an independent prognostic factor for cancer." (PMID 39895790, 2025). "The novel serine/threonine kinase NEK6 is highly expressed in various cancers and affects the prognosis of patients." (PMID 39895790, 2025). "Pancancer analysis via the online TIMER2.0 and UALCAN datasets revealed that NEK6 was highly expressed in most human cancers and that NEK6 was highly expressed in OC tumors." (PMID 39895790, 2025). "In this study, we found that NEK6 was highly expressed in most human cancers, including OC, via a pancancer analysis with bioinformatics tools." (PMID 39895790, 2025). "Together, these results suggest that preventing DNA DSBs repair by NEK6 inhibition enhances the vulnerability of cancer cells to CDK4/6 inhibition." (PMID 41560755, 2025). "For instance, NEK6 overexpression has been shown to enhance the survival of cancer cells under hypoxic conditions, potentially contributing to tumor progression and metastasis." (PMID 41154634, 2025). "Nek6 is highly expressed in different malignant tumors, and elevated expression correlates with tumor stage and poor prognosis." (PMID 38469292, 2024). "The expression of Cd52, Snap29, Mcoln1 and Nek6 genes, known to promote tumorigenesis in different cancer types, was up-regulated in peritoneal TCL1-Tg CLL cells." (PMID 38469292, 2024). "Our investigation revealed a marked increase in NEK6 expression intensity in cancer tissues compared to paraneoplastic tissues." (PMID 39256367, 2024). "Overexpression of NEK6 has been reported in a variety of human cancers and plays an oncogenic function." (PMID 37835513, 2023). "The inhibition of NEK6 has been seen as an executable target in cancer, and inhibitors of this kinase have already been explored in other types of cancer." (PMID 36672191, 2023). "In recent years, the expression and kinase activity of NEK6 have been reported to be enhanced in several malignant human cancer cells, including liver cancer, prostate cancer, gastric cancer, breast cancer, ovarian cancer, and retinoblastoma cancer." (PMID 35096064, 2022). "By targeting miR-370-3p, Circ-NEK6 promotes cancer cell invasion, metastasis, and disease progression via transmembrane signaling receptor “frizzled family receptor 8 (FZD8)” upregulation and “Wnt signaling” pathway activation in TC." (PMID 36230649, 2022). "In our study, NEK6 was higher in multiple types of cancer tissues than in corresponding normal tissues." (PMID 35898455, 2022). "NEK6 is up-regulated in malignant tumors and cancer cells; therefore, it is regarded as a pivotal regulatory factor in tumorigenesis." (PMID 33488591, 2020).
cancer (continued). "Conversely, NEK6 down-regulation was able to reduce the migration and proliferation of cancer gastric cells." (PMID 32294979, 2020). "Of additional interest from a therapeutic standpoint, the potent HSP70 family inhibitor VER-155008, produced cancer-specific spindle multipolarity, with specific Nek6 inhibitors also under development." (PMID 31506331, 2019). "Nek6 and Hsp72 are also required for centrosome clustering in cancer cells with amplified centrosomes, presumably through similar mechanisms to those that promote K-fiber stabilization." (PMID 29250521, 2017). "Curiously though, most of the functions described for Nek6 and Nek7, at least in terms of mitotic progression in cancer cell lines, are very similar." (PMID 29250521, 2017). "Consistently, knockdown of Nek6 suppressed anchorage-independent growth of several carcinoma cell lines, including colon (HCT-15), stomach (NCI-N87) and cevix (HeLa), as well as growth of HeLa xenografts." (PMID 22040655, 2011). "Pin1 overexpression is prevalent in human cancers, including liver cancer, and upregulation of Nek6 mRNA was found to correlate with Pin1 upregulation in 70% of hepatic cell carcinomas." (PMID 17727698, 2007). "In addition to NEK2, which is the most overexpressed NEK in human cancers, including GI cancers, NEK6 overexpression has been reported in various human cancers, making it an attractive target for antitumor therapy." (PMID 40076620, 2025). "NEK6 has been reported to be highly expressed in various human cancers." (PMID 39895790, 2025). "To confirm whether NEK6 inhibitors induce DNA damage in cancer cells by inhibiting DNA repair, we tested the effect of NEK6 inhibitor on palbociclib-mediated induction of DNA double-strand breaks (DSBs)." (PMID 41560755, 2025). "As an important member, NEK6 has also been found to be overexpressed in various cancers." (PMID 39895790, 2025). "Finally, as alluded to above, NEK6 interaction with microRNAs such as miR-26a-5p, miR-506-3p and miR-323a-3p provides an additional layer to its regulatory role in cancer cell proliferation and apoptosis." (PMID 41154634, 2025). "Although several studies have suggested that NEK6 is associated with malignant tumor features, the chemoresistance mediated by NEK6 has not been fully elucidated." (PMID 39256367, 2024). "NEK6 inhibition does not alter the cell cycle of normal cells, only cancer cells, indicating that the inhibition of NEK6 may provide therapeutic advantages in cancer treatment." (PMID 36672191, 2023). "For future studies, we suggest that an eventual combination of NEK6 inhibitors with MTX may be an interesting strategy for reducing the resistance of cancer cells to the chemotherapeutic agent." (PMID 36672191, 2023). "A recent study emphasized that NEK6 is an executable target in cancer." (PMID 36672191, 2023). "Nek6 has also been found to play a role in the cytoskeletal gateway of drug resistance via directly interacting with Guanylate Binding Protein 1, creating drug-resistant cancers." (PMID 35409400, 2022). "Under reduced serum conditions, knockdown of Nek6 induces premature cancer cell senescence." (PMID 35409400, 2022). "The NIMA (never in mitosis, gene A)-related kinase-6 (NEK6), which is implicated in cell cycle control and plays significant roles in tumorigenesis, is an attractive target for the development of novel anti-cancer drugs." (PMID 30375481, 2018). "Indeed, several NEK proteins such as NEK2, NEK6, and NEK8 are overexpressed or mutated in various types of cancer." (PMID 27602754, 2016). "In the present study we show that beyond polyps Nek6 is also detected in carcinoma." (PMID 27441409, 2016).
cancer (continued). "Furthermore, it has been shown that the over expression of Nek6 can endorse cell alteration while suppression of Nek6 resulted in inhibition of anchorage-independent growth and stirred apoptosis in most cancer cells." (PMID 24587765, 2014). "Furthermore, NEK6 protein was strongly stained in most of the cancer tissues, but showed less mRNA signal compared to the remaining six genes." (PMID 18827816, 2008). "Like Nek6, Nek2 is also upregulated in various cancer cell lines, as well as primary breast tumours, and the hope is that interfering with mitotic Neks may arrest cell growth or promote apoptosis in a tumour-specific manner." (PMID 17727698, 2007). "Furthermore, we found that NEK6 was positively co-expressed with these immune checkpoints, which may partially explain the cancer-promoting role of NEK6 by analyzing the correlation between immune checkpoints and NEK6." (PMID 35898455, 2022). "In this context, we elucidate the structural information of Nek6, which may be a new drug target for developing inhibitors against cancers by means of a homology modeling approach pursued by a molecular dynamic simulation in order to explore the stability of the protein." (PMID 24587765, 2014). "Hence, Nek6 has emerged as a therapeutic target for drug development towards cancer." (PMID 24587765, 2014). "In contrast, stable ectopic expression of NEK6 in HEC-1A and ishikawa cell lines desensitized cancer cells to palbociclib, evidenced by an increased IC50 and clonogenic assays." (PMID 41560755, 2025). "In cancers, NEKs such as NEK1, NEK2, NEK6, and NEK11 promote genome instability and tumor progression, while others, like NEK1, paradoxically offer opportunities for radiosensitization." (PMID 41154634, 2025). "For example, during cancer metastasis, NEK5 activity is coordinated with that of other NEK family members, such as NEK4 and NEK6, to orchestrate microtubule organization." (PMID 41154634, 2025). "A possible role can be played by the miR-26b target, Nek6, coding for a kinase involved in the initiation of mitosis; the overexpression of Nek6, already observed in different tumors, could contribute to the avoidance of cellular senescence and promote cancer progression." (PMID 23650540, 2013). "Although targeting other proteins that play roles in centrosome clustering can induce multipolar spindles and reduce cancer cell growth, such as Hsp72, Nek6 or STAT3, no therapeutic approaches have yet reached clinical trials." (PMID 39789388, 2025). "For this reason, it is essential to understand the survival pathways that NEK6 regulates in CRPC, because NEK6 inhibitors may be used as a cancer therapy." (PMID 36672191, 2023). "NEK6 phosphorylation of HSP72 is required to cluster amplified centrosomes, whilst their depletion in non-cancer derived cells does not affect spindle formation or mitotic progression, thus making them attractive cancer-specific targets." (PMID 31506331, 2019). "In data not shown here, we also found higher levels of NEK6 protein in advanced cancer compared to early-stage samples by immunohistochemistry." (PMID 18827816, 2008). "NEK6 (Never in Mitosis A (NIMA) related kinases 6), as a cyclin, promotes cancer cell proliferation and cancer progression." (PMID 35898455, 2022). "NEK6 (Never In Mitosis A (NIMA) related kinases 6), a cyclin, promotes the invasion and metastasis of various cancers by regulating cell proliferation and apoptosis." (PMID 35898455, 2022).
tumor (21 papers, 2008 to 2025). "We found that HEC-1A-shNC-derived tumor growth could be suppressed by palbociclib, while loss of NEK6 significantly enhanced the growth inhibition." (PMID 41560755, 2025). "We found that NIMA-related kinase-6 (NEK6) levels determine the anti-tumor effects of CDK4/6 inhibitors and that NEK6 was a synthetic lethal target of CDK4/6 inhibitors in EC." (PMID 41560755, 2025). "Overexpression of NEK6 has been observed in several solid human tumors, promoting tumor proliferation, invasion, and metastasis." (PMID 39256367, 2024). "Nonetheless, the KMPlot data suggest potential avenues for exploring the tumor-suppressive qualities of NEK6, NEK7, and NEK9 in kidney renal cell carcinoma." (PMID 37046733, 2023). "Collectively, these results suggest that FAM13A-AS1 promotes tumor growth by competing miR-141-3p with NEK6." (PMID 35402517, 2022). "Among the ten tumor-related genes used in the risk model, TRIM15, NEK6, ISG15, RFC2, and NR1H3 were upregulated." (PMID 36189312, 2022). "In this study, NEK6 was highly expressed in Her2+BC tissues and significantly correlated with the tumor stage, indicating poor RFS, DFS, and PPS of BC." (PMID 35368696, 2022). "Animal experiments have also shown that low expression levels of NEK6 can lead to tumor cell reduction." (PMID 35105934, 2022). "The relationship between tumor immune cell infiltration and immune checkpoint molecule expression and NEK6 expression was also further analyzed." (PMID 35898455, 2022). "By analyzing the transcriptome of the TCGA cohort, we noticed that the expression level of NEK6 in RCC was significantly increased in tumor samples, compared with the adjacent normal tissues." (PMID 35402517, 2022). "Previous studies showed overexpression of NEK7 and NEK6 in a series of human tumor types, and the biological roles of NEK6 and NEK7 were extremely similar in cell cycle and cell proliferation enhancement." (PMID 34295827, 2021). "Previous studies showed that overexpression of NEK6 was detected in a range of human tumor types, including breast, lung, liver, gastric and colorectal cancers." (PMID 34295827, 2021). "Immunohistochemistry showed high expression of INHBA and NEK6 proteins in 14 of 20 and 24 of 27 tumour tissues, respectively, whereas IGFBP7 and LUM proteins showed little immunoreactivity in tumour tissue relative to adjacent healthy tissue (data not shown)." (PMID 18827816, 2008). "Furthermore, the NEK6 levels in the tumor tissues of OC patients were detected via RT‒qPCR and Western blotting." (PMID 39895790, 2025). "Specifically, we revealed that the inhibition of NEK6 by genetic modification or ZINC05007751, a NEK6 selective inhibitor, could enhance the anti-tumor effects of palbociclib (a CDK4/6 inhibitor) in cell lines, patient-derived organoids and mouse models of EC." (PMID 41560755, 2025). "Recent studies have revealed a potential role for NEK6 in conferring resistance to tumor therapy." (PMID 39256367, 2024). "Nek6 is also targeted and downregulated by the microRNA miR-141-3p, a tumour-inhibiting miRNA." (PMID 35409400, 2022). "Nek6 is a kinase involved in the initiation of mitosis and is overexpressed in various tumours." (PMID 24651473, 2014). "Furthermore, among a total of 110 OC patients, IHC revealed that NEK6 was positively stained in tumor tissues and negatively stained in normal tissues and that its overexpression was correlated with clinicopathological factors, such as histological grade and metastasis." (PMID 39895790, 2025). "We further demonstrated that combined inhibition of NEK6 and CDK4/6 resulted in marked suppression of tumor growth in vitro and in vivo." (PMID 41560755, 2025). "Five drugs and two molecules targeting NEK6 and NEK7 have already exhibited anti-tumor effects in investigations or clinical trials." (PMID 38902711, 2024). "Here, we aimed to investigate the function of NEK6 gene in HNSCC and its effect on tumor immune infiltration." (PMID 35898455, 2022).
tumor (continued). "IHC staining revealed 67.27% (74/110) moderate and/or strong NEK6 staining in tumor tissues, 32.73% (36/110) weak staining, and negative or weak NEK6 staining in normal ovaries." (PMID 39895790, 2025). "Therefore, NEK6 regulates CDK2 and Bcl-2 through YBX1, which synergizes with CDK4/6 inhibitors to inhibit tumor growth." (PMID 41560755, 2025). "Additionally, according to the UALCAN database, the mRNA expression levels of NEK2, NEK3, NEK4, NEK5, NEK6, and NEK8 were significantly positively correlated with the tumour grade, whereas that of NEK10 was inversely associated with this factor." (PMID 38706902, 2024). "Interestingly, the expression levels of NEK2, NEK6, and NEK10 were not only remarkably correlated with the tumor stage but also with the molecular subtype." (PMID 35368696, 2022). "Our study shows that immune cell infiltration recruited by NEK6 has both positive and negative effects on tumor patients." (PMID 35898455, 2022). "The overexpression of NEK6 has been described in castrated males and female animals, representing absent systems of androgen hormones, resulting in increased tumor formation." (PMID 32294979, 2020). "However, purine supplementation rescued tumor volume after DOX treatment and NEK6 knockdown." (PMID 39256367, 2024). "At the same time, NEK6 and NR1H3 might be downregulated in tumor tissues." (PMID 36189312, 2022). "The circular RNA of NEK6 may increase the expression of Frizzled class receptor 8 (FZD8), a constituent of the Wnt signaling pathway, since it binds and inhibits mRNA-370-3p, a tumor suppressor." (PMID 32294979, 2020).
infection (1 paper, 2020). The state of being infected such as from the introduction of a foreign agent such as serum, vaccine, antigenic substance or organism. "Afterwards, potential candidates were further screened by Western blotting, and NEK6 was selected due to its low expression in M. tuberculosis-resistant macrophages after infection." (PMID 32487755, 2020). "Notably, BCL-2 and its family genes (BCL-XL, BCL-W, and MCL-1) were upregulated during infection with gamma-irradiated M. tuberculosis infection in BMDMs from WT mice but not in those from NEK6-deficient mice." (PMID 32487755, 2020). "Transfection of miR-325-3p or infection with gamma-irradiated M. tuberculosis can also downregulate LNX1, resulting in the accumulation of NEK6 in macrophages." (PMID 32487755, 2020). "In contrast, the NEK6 K174A mutant could not be ubiquitinated during infection." (PMID 32487755, 2020).
NEK6 also shares sentences with these, for which no sentence is quoted: laryngeal carcinoma (2 papers); liver cancer (2); vitiligo (2); adenocarcinoma (1); allergic rhinitis (1); breast invasive carcinoma (1); Colon (1); diabetes (1); diffuse large B-cell lymphoma (1); emphysema (1); endometrioid adenocarcinoma (1); esophageal carcinoma (1); heart failure (1); hypothyroidism (1); lung fibrosis (1); Lung squamous cell carcinoma (1); lymphoid neoplasm (1); non-small cell lung carcinoma (1); polycystic kidney disease (1); prediabetes (1); renal carcinoma (1); tobacco use disorder (1); uterine corpus endometrial carcinoma (1).